DPP4 (dipeptidyl peptidase 4)
Diseases named in the same sentence as DPP4 in open-access papers (continued):
Sharing a sentence is not in itself a finding about the gene and the disease.
COVID-19 (continued). "The possible role of dipeptidyl peptidase 4 (DPP-4) as a receptor for SARS-CoV-2 raises the potential for DPP-4 inhibitors in diabetic COVID-19 patients, but further research is needed to investigate their role." (PMID 32868984, 2020). "Similar to the ACE2 receptor, human CD26 (also called DPP4) is also suggested as the potential binding site for COVID-19." (PMID 32585855, 2020). "Exome sequencing and analysis of a smaller cohort of 131 COVID-19 patients from Italy for genetic variants of TMPRSS2, PCSK3, DPP4, and BSG genes identified 17 variants." (PMID 33092637, 2020). "Some groups have shown that patients with COVID-19 who were on Dipeptidyl peptidase 4 inhibitor (DPP-4is) had a similar disease outcome as those who were not." (PMID 33335527, 2020). "Increased DPP4 expression and activity are associated with TDM2, obesity, and metabolic syndrome, all of which have been related to COVID-19 susceptibility and severity." (PMID 33050220, 2020). "Targeting DPP4 has been thus considered as a pharmacologically reasonable strategy in the case of severe respiratory diseases related to coronaviruses and COVID-19." (PMID 33584268, 2020). "Further studies regarding the effect and prognosis of DPP4 inhibitors in patients with DM and COVID-19 are warranted." (PMID 33297431, 2020). "DPP4 inhibitors are widely used clinically and have been shown to enhance clinical outcomes and reduce mortality in diabetes mellitus patients with COVID-19." (PMID 33324223, 2020). "Targeting DPP4 to inflect natural viral dynamics has been thus suggested as a pharmacologically reasonable strategy in the case of COVID-19, as well as other severe respiratory diseases related to coronaviruses." (PMID 32456064, 2020). "Consequently, the goal of this systematic review is to investigate the most recent data on the effect of DPP-4i (dipeptidyl peptidase-4 inhibitor) medications on clinical outcomes, mainly mortality among COVID-19 patients." (PMID 41899041, 2026). "Furthermore, host receptors documented in COVID-19 individuals include dipeptidyl peptidase-4 (DPP4), transferrin receptor (TFRC), and extracellular high mobility group box 1 (HMBG1)." (PMID 41488148, 2025). "Diabetic patients face higher risks of severe COVID-19 outcomes, and DPP-4 inhibitors’ anti-inflammatory effects could improve their prognosis." (PMID 40509444, 2025). "Considering these facts, the reduced number of lymphocytes—the main cellular source of soluble DPP4—may explain the low serum DPP4 levels observed in COVID-19 patients." (PMID 41464188, 2025). "Intriguingly, computational models suggest a robust molecular interaction between the SARS-CoV-2 S1 subunit and DPP-4, while COVID-19 may share infection patterns with SARS-CoV and MERS-CoV." (PMID 40509444, 2025). "Recent studies suggest that DPP-4 inhibition may protect against COVID-19 by reducing viral entry and replication." (PMID 40869643, 2025). "It has been suggested that the inhibition of DPP4 could decrease COVID-19 severity by reducing inflammation and enhancing tissue repair beyond glucose lowering." (PMID 40766923, 2025). "Given that SARS-CoV-2 infects humans via the ACE2 receptor, it is plausible to hypothesize that DPP-4 inhibitors may have a greater impact on COVID-19 mortality than other agents." (PMID 40869643, 2025). "A multicenter retrospective cohort study conducted in Saudi Arabia found no significant impact on mortality reduction or ICU treatment, whereas an observational meta-analysis reported that DPP-4 inhibitor use reduced COVID-19-related mortality by approximately 50%." (PMID 40869643, 2025). "Beyond glucose metabolism, DPP-4 functions as an immunomodulator; its inhibition reduces inflammatory cytokines (e.g., IL-6, TNF-α) and improves endothelial function, potentially mitigating severe COVID-19–related inflammation and thromboembolic risk." (PMID 40869643, 2025). "Results from previous studies on the use of DPP-4 inhibitors in COVID-19 patients have been mixed." (PMID 40869643, 2025).
COVID-19 (continued). "The findings of these two cases indicate that COVID-19 and DPP-4 inhibitors may interact and contribute to the development of BP." (PMID 40895902, 2025). "However, a meta-analysis provided by Zein and Rafaello based on 11 studies revealed decreased mortality in the group of COVID-19 patients who were treated with DPP4 inhibitors." (PMID 39273582, 2024). "Some studies have shown DPP-4 inhibitors mortality benefits in diabetic patients with COVID-19." (PMID 38536830, 2024). "Interestingly, our data revealed an association between severe coronavirus disease 2019 (COVID-19) and DDP4, namely that DPP4 levels increased in the plasma of patients with COVID-19 and were correlated with age and disease progression." (PMID 37728586, 2024). "Furthermore, changes in the expression of the ACE2, TMPRSS2, CLEC4M and DPP4 genes, observed in TC, also occur in COVID-19." (PMID 39767735, 2024). "DPP-4 inhibitors showed a non-significant decrease in risk for COVID-19 death (OR 0.761; 95% CI 0.568–1.019)." (PMID 38536830, 2024). "We investigated DPP4 levels in patients with COVID-19 using the SomaLogic protein assay." (PMID 37728586, 2024). "Our multivariate regression models showed DPP-4 inhibitors were associated with statistically non-significant decrease in odds for COVID-19 death (OR 0.761; 95% CI 0.568–1.019)." (PMID 38536830, 2024). "We also show a relationship between age, DPP4, and the severity of COVID-19." (PMID 37728586, 2024). "However, patients with ARDS were more likely to have been prescribed DPP4 inhibitors prior to their admission for COVID-19 (p = 0.008)." (PMID 37374918, 2023). "CHIs may reduce the COVID-19 severity by reducing the SARS-CoV-2 entry points at ACE2/DPP4/CD147 axis in the initial phase and immunomodulation in the late phase of the disease by suppressingTLR4/NF-kB signaling pathway." (PMID 37383608, 2023). "Since DPP4 is a serine protease, DPP4 inhibitors may also be developed as therapeutic drugs targeting COVID-19." (PMID 37645223, 2023). "For those treated with GLP-1 Ras, 2.8% were admitted due to COVID-19, and 1.5% for other reasons, while among the subjects treated with DPP-4 inhibitors (DPP-4is), the respective percentages were 3.6% for COVID-19-related hospitalization and 2.0% for other reasons." (PMID 37626788, 2023). "This suggests a probable role of sDPP-4, in addition to membrane-bound DPP-4, in COVID-19 severity." (PMID 37064327, 2023). "Currently, very few studies have been performed with patients taking DPP-4 inhibitors for COVID-19." (PMID 37064327, 2023). "Recently, there has been interest in using DPP4 inhibitors to treat COVID-19." (PMID 37896834, 2023). "Overall, DPP4 inhibitors are a promising new class of medications that could be used to prevent and treat COVID-19." (PMID 37896834, 2023). "DPP-4 inhibitors may also reduce blood glucose levels and improve diabetogenic conditions, which appears to be a comorbidity in COVID-19." (PMID 37064327, 2023). "Finally, we offer an update on the DPP4 inhibitors approved by the European Medicine Agency and the U.S. Food and Drug Administration, ending with the effect of the said inhibitors on COVID-19 patients." (PMID 36009573, 2022). "Role of these kinases, oxidoreductases, upregulation of DPP4, and inhibition of PI3K/AKT signaling pathway have been highlighted in multiple studies in the treatment of Covid19." (PMID 35700199, 2022). "Study has been reported that there may be a tight interaction between the COVID-19 spike glycoprotein and DPP4." (PMID 36329841, 2022). "It has been hypothesized that inhibition of DPP4 by sitagliptin may reduce the propagation of hyperinflammation and cytokine storm in COVID-19." (PMID 36355535, 2022). "As can be seen, the therapeutic benefits of DPP4 inhibitors may shed new light for DKD complicated with COVID-19 patients, and more research is warranted to fully evaluate their effect." (PMID 36341356, 2022).
COVID-19 (continued). "Together, these results support a scientific hypothesis linking DPP-4 inhibitors with prognosis in patients with COVID-19." (PMID 35017617, 2022). "Therapy with metformin, DPP-4 inhibitors, SGLT2 inhibitors, arGLP-1 before the infection and anti-COVID-19 vaccination were associated with a lower CFR, while SU and insulin therapy was associated with a higher CFR due to COVID-19." (PMID 36017317, 2022). "The severity of COVID-19 was also correlated with the down-regulation of DPP4." (PMID 36553622, 2022). "It is hypothesized that DPP4 inhibitors might attenuate COVID-19-related cardiovascular injury including arrhythmia, acute coronary syndrome and heart failure." (PMID 36145576, 2022). "Clinical and pre-clinical studies demonstrated that RAAS-blocking agents can be safely used during a SARS-CoV-2 infection but it is unknown if DPP-4 inhibitors or SGLT2-blockers may promote COVID-19 by increasing the host viral entry enzymes ACE2 and TMPRSS2." (PMID 35331159, 2022). "Altogether, these findings indicate that high glucose levels might favor virus replication and immune dysregulation and that DPP4 could participate in the worst clinical findings shown in COVID-19 diabetic patients, through regulation of both phenomena." (PMID 36009573, 2022). "However, increasing evidence illustrates that DPP4 inhibitors have a beneficial effect on the clinical outcome of patients by reducing COVID-19 complications, improving recovery, and reducing mortality." (PMID 36009573, 2022). "Although this hypothesis needs to be further elucidated, data from clinical studies indicate that DPP4 participates in the coronavirus disease 2019 (COVID-19) physiopathology and therefore is a therapeutic target for this disease." (PMID 36009573, 2022). "Although there is no experimental evidence suggesting that hyperglycemia-induced aberrant glycosylation of DPP4 may play a role in COVID-19 physiopathology, several pieces of information shed light on this hypothesis." (PMID 36009573, 2022). "Although no clinical trials have been conducted to date to evaluate their efficacy, anti-DPP4 antibodies might be considered an interesting approach, worth being tested for dealing with COVID-19." (PMID 36009573, 2022). "All three CHM formulas not only affect ACE but also blood sugar control related target proteins such as DPP4 and GHSR, meaning that they can help reduce the risk of precipitating hyperglycemia caused by COVID-19 as well as lower the blood sugar level of pre-existing DM." (PMID 35890093, 2022). "Considering the role of DPP4 on COVID-19 physiopathology, it can be speculated that inhibition of DPP4 might protect from SARS-CoV-2 infection or could benefit its clinical outcome." (PMID 36009573, 2022). "Current evidence does not indicate safety issues associated with the use of DPP4 inhibitors in COVID-19 patients with DM." (PMID 35370750, 2022). "Here, SARS-CoV-2 can also gain access through dipeptidyl peptidase-4 (DPP4) that is inhibited from activated AhR, which could explain the apparent protection of smokers from COVID-19." (PMID 35203299, 2022). "The binding of S protein of COVID-19 with DPP4 was the starting point of COVID-19." (PMID 34996987, 2022). "Therefore, emerging of clinical trials is warranted to confirm the role of ACE2 and DPP4 modulators in COVID-19-induced AKI." (PMID 34629845, 2021). "Whether the level of ACE2 and DPP-4 in peripheral blood may represent valuable biomarkers to monitor recovery from COVID-19 or the onset of PPCS is unclear." (PMID 34200325, 2021). "Some evidence indicates that DPP-4 inhibitors might inhibit the entrance of coronavirus into the airways, which suggests an additional therapeutic approach to COVID-19 treatment." (PMID 34200325, 2021). "Finally, there are now six studies that have investigated the effects of DPP4 inhibitors on the outcomes of COVID-19 in diabetic patients." (PMID 33648564, 2021).
COVID-19 (continued). "Human DPP-4/CD26 is manifested to interplay with the S1 domain of the COVID-19 spike glycoprotein, representing that it might be a vital virulence factor in COVID-19 infection." (PMID 34944659, 2021). "Moreover, it cannot enter cells with conventional COVID-19 entry receptors such as aminopeptidase N and dipeptidyl peptidase 4 (DPP4)." (PMID 34853605, 2021). "To date, dipeptidyl peptidase 4 (DPP4), which is highly expressed in different tissues, mainly in lung type II alveolar cells, is regarded as an entry point for SARS-CoV-2 and is associated with poor clinical outcomes in COVID-19 patients." (PMID 34568081, 2021). "Therefore, emerging of clinical trials is warranted to confirm the role of ACE2 and DPP4 modulators in COVID-19 AKI." (PMID 34629845, 2021). "The Coronado study showed no independent association between severity of COVID-19 and use of DPP4 inhibitors, but we should emphasize that they only considered iDPP4 use prior to admission." (PMID 33648564, 2021). "In this study, we systematically reviewed the relationship between viral cell surface receptors (ACE2, AXL, CD147, DC-SIGN, L-SIGN and DPP4) and SARS-CoV-2 infection risk, and emphasized the implications of ACE2 on SARS-CoV-2 infection and COVID-19 pathogenesis." (PMID 34867819, 2021). "Moreover, CD26/DPP4 was also suggested as a (co-)receptor for SARS-CoV-2, the virus causing the respiratory syndrome COVID-19 since the closely related virus MERS-CoV utilizes CD26/DPP4 for viral entry." (PMID 34885056, 2021). "Thus, further experimental evidence is needed to identify the physiological involvement of the DPP4 receptor in mediating viral entry in order to validate the potential use of DPP4 inhibition as a COVID-19 treatment." (PMID 33498183, 2021). "Other potential actors may also contribute to the link between COVID-19 and DN, such as mitochondrial glutathione, vitamin D, and DPP4." (PMID 34360529, 2021). "Some clinical trials on DPP4 inhibitors in COVID-19 are ongoing." (PMID 34955820, 2021). "Based on our results it is suggested that the modulation of DPP4 might interfere with the infection and/or progression of COVID-19 and therefore might represent a therapeutic strategy." (PMID 33796097, 2021). "A large interface has been predicted in the docking of DPP-4/SARS-CoV-2 spike protein, and it seems that the S1 domain of COVID-19 spike glycoprotein may interact with the human DPP4, a key immunoregulatory factor for hijacking and virulence." (PMID 34360529, 2021). "Likewise, sitagliptin (Januvia; 2006), another DPP-4 inhibitor, is also being tested in COVID-19-positive diabetic patients (NCT04365517)." (PMID 32718020, 2020). "Therefore, the researches of DPP-4 inhibitors have exciting potential for diabetic patients infected with COVID-19." (PMID 33031311, 2020). "The dual effects of mast cells in viral infections could introduce further arguments and controversies in the debate about the use of DPP4 inhibitors as a potential protective strategy against severe COVID-19 manifestations." (PMID 32456064, 2020). "The anti-inflammatory effects of dipeptidyl peptidase-4 inhibitor may benefit patients with DM and COVID-19." (PMID 33297431, 2020). "Various authors emphasized anti-inflammatory properties of DPP-4 inhibitors with conflicting opinions on whether these effects are beneficial or detrimental in patients with COVID-19." (PMID 32848788, 2020). "Therefore, the research of DPP-4 inhibitors can be used as a new strategic direction to prevent COVID-19." (PMID 33031311, 2020). "Therefore, we are trying to conduct a meta-analysis to provide high-quality evidence for the treatment of COVID-19 diabetes patients with DPP-4 inhibitors, and to inject new impetus into the clinical response to the COVID-19 epidemic." (PMID 33031311, 2020). "Irregardless of DPP4 role as co-receptor, gliptins might help prevent CV complications in COVID-19 due to their anti-inflammatory effects at vascular level." (PMID 32848769, 2020).
COVID-19 (continued). "Therefore, this article aims to explore the effectiveness and safety of DPP-4 inhibitors in the treatment of COVID-19 patients with DM." (PMID 33031311, 2020). "Several benefits of DPP4 inhibitors for patients with DM who develop COVID-19 have been proposed, including reduction of cytokine overproduction, downregulation of macrophage activity, enhancement of GLP-1 anti-inflammatory activity and stimulation of pulmonary anti-inflammatory effects." (PMID 33297431, 2020). "The potential role of DPP-4 in the pathogenesis of COVID-19 is a subject of the ongoing debate." (PMID 32848788, 2020). "A recent study has suggested a few other receptors such as DPP4, ANPEP, ENPEP, and TMPRSS2 as co-receptors/auxiliary proteins to complement ACE2 in initiating SAR-CoV-2 infection." (PMID 33330620, 2020). "Further research is necessary to utilize DPP-4 as a therapeutic target for COVID-19." (PMID 32325767, 2020). "Additionally, large-scale international comparative studies could elucidate regional differences in outcomes, while mechanistic studies are needed to clarify the pleiotropic effects of DPP-4 inhibition in COVID-19." (PMID 40869643, 2025). "This suggests that DPP-4 inhibitors may help prevent the progression of COVID-19 to severe disease." (PMID 40869643, 2025). "Other antidiabetics such as dipeptidyl peptisase-4 (DPP-4) and sodium-glucose cotransporter 2 (SGLT2) inhibitors, glucagon-like peptide-1 (GLP-1) agonists, thiazolidinediones, and sulfonylureas also reduced the risk of mortality in diabetic patients with COVID-19." (PMID 38378550, 2024). "However, DPP4 inhibitors also exert anti-inflammatory effects, which could be beneficial in patients exposed to cytokine storms due to COVID-19." (PMID 37374918, 2023). "Thus, DPP4 inhibitors show potential to reduce the severity of COVID-19 disease and could be a potential choice for COVID-19 treatment in diabetic subjects." (PMID 37064327, 2023). "Care must be exerted while recommending most commonly prescribed anti-diabetic drugs such as biguanides, SGLT2 inhibitors, DPP-4 inhibitors, sulfonylureas, and insulin as recent reports have observed that these drugs might exacerbate clinical conditions in COVID-19 cases." (PMID 36839456, 2023). "A recent epidemiological study stated that the administration of DPP4 inhibitors might not show any risk effect of hospitalization in 403 COVID-19 patients along with T2DM." (PMID 36839456, 2023). "In this context, the hypothesis of whether DPP-4 inhibition increases susceptibility to COVID-19 infection and whether it reduces significant complications such as ARDS, which represents the leading cause of death in COVID-19 patients, has been brought up." (PMID 36199855, 2022). "Interestingly, Imbalance of the RAAS and direct effect of DPP4 promote vascular system damage, which result diabetic patients might be more affected by COVID-19, However, the interaction mechanism between DPP4 and RAAS (including ACE2) has not clear." (PMID 35399920, 2022). "Using the hiPSC-derived hLORGs, they identified two immunotherapeutic candidates for COVID-19 treatment, a tetravalent neutralizing antibody (15033-7) targeting the spike protein, and a synthetic peptide homologous to the dipeptidyl peptidase-4 (DPP4) receptor on host cells." (PMID 36077471, 2022). "Therefore, DPP-4 inhibition may prevent lung fibrosis progression and reduce mechanical complications of COVID-19." (PMID 36289885, 2022). "Higher levels of DPP4 might be correlated with the occurrence and severity of COVID-19." (PMID 34955820, 2021). "Thus, it is possible that DPP-4 inhibitors have a beneficial effect on COVID-19 compared with supportive care alone, but this effect is eliminated when other therapies such as remdesivir and dexamethasone are added, as was for most of the patients in our study." (PMID 35002970, 2021).